BRCA1 (BRCA1 DNA repair associated)
Diseases named in the same sentence as BRCA1 in open-access papers (continued):
Sharing a sentence is not in itself a finding about the gene and the disease.
breast cancer (continued). "Previous studies have reported that mammary tumors spontaneously generated in Brca1-mutant mice can be orthotopically transplanted into female mice without losing their original phenotype, gene expression profile, or sensitivity to anticancer agents 10,27." (PMID 33767581, 2021). "For women with BRCA1, the cumulative lifetime risk of CBC 20 years after the initial breast cancer diagnosis has been estimated to be approximately 40%." (PMID 34573353, 2021). "For BRCA1/2 mutant breast cancers, PARPi olaparib and talazoparib are now FDA-approved monotherapies." (PMID 33662042, 2021). "In this group, 92/116 (79.3%) women with breast cancer and a MS of ≥40 tested positive for a BRCA1/2 PV (BRCA1 (n = 67) or BRCA2 (n = 25))." (PMID 34439310, 2021). "Meanwhile, to confirm the effect of VPA on malignant cells, we also tested the expression of Rad51 and BRCA1 in several breast cancer cell lines including MCF7, MDA-MB-231, and EUFA423." (PMID 33842359, 2021). "For example, germline BRCA1 promoter deletions have been confirmed in familial breast cancer patients from the United Kingdom and Australia." (PMID 34926299, 2021). "Several studies in breast cancer suggest an association between BRCA mutation status and increased immune cell infiltration, especially for the BRCA1-mutated tumors." (PMID 34067105, 2021). "Although BRCA1 and BRCA2 are the most well-known risk genes associated with about a 20-fold increased breast cancer risk, they only account for 20% of familial breast cancer due to the low frequency of mutations." (PMID 34069208, 2021). "Germline variants in ATM, BRCA1, BRCA2, CHEK2, and PALB2 were associated with a high risk of breast cancer; a more modest risk was associated with BARD1 and RAD51C." (PMID 34445631, 2021). "By the age of 70 years, BRCA1 and BRCA2 carriers were previously found to have average cumulative risk of contralateral breast cancer of 83% and 62%, respectively." (PMID 34206661, 2021). "Twenty founder alleles in BRCA1, BRCA2, CHEK2, NBN, PALB2 and RECQL genes are responsible for the majority of hereditary breast cancers in Polish women." (PMID 34461861, 2021). "Referring to the value of some prognostic genes, such as BRCA1/2 genes, in breast cancer evolution, the exploitation of ABC transporter genes in tumorigenesis is of great interest." (PMID 33801148, 2021). "Pathogenic mutations in the BRCA1 and BRCA2 genes confer high risks of breast, ovarian, and contralateral breast cancer (CBC)." (PMID 34575624, 2021). "The Consortium of Investigators of Modifiers of BRCA1 and BRCA2 (CIMBA), established in 2006, has provided a large number of BRCA mutations related to breast cancer." (PMID 34065872, 2021). "It is well known that monogenic BRCA1 and BRCA2 variants predispose women to breast cancer, but this population is small—perhaps a few per thousand in the general population." (PMID 34440279, 2021). "The testing performed consisted of 43% (3/7) gene testing for BRCA1/2 only, 43% (3/7) breast cancer panel testing and 14% (1/14) predictive BRCA1 test." (PMID 33637119, 2021). "In the current study, we evaluated the frequency of 20 recurrent mutations in six genes (BRCA1, BRCA2, CHEK2, PALB2, NBN and RECQL) in 165 men diagnosed with breast cancer in Poland." (PMID 34461861, 2021). "In line with the molecular subtyping result, different samples display distinct expression patterns of these genes, indicating great intertumor heterogeneity among both BRCA1 germline and somatic mutant breast cancers." (PMID 34815798, 2021). "Taken together, these data suggest that higher BRCA1 expression confers some growth advantage onto cancer cells, possibly reflecting the poor recurrence-free survival rate in breast cancer patients with higher BRCA1 expression." (PMID 33888730, 2021).
breast cancer (continued). "The PALB2 (partner and localizer of BRCA2) mutation was found to be associated with an increased risk of breast cancer and one of the most common mutations, after BRCA1 and BRCA2, in non-BRCA1/2 breast cancer patients." (PMID 34439348, 2021). "The effects on these subgroups are subtle, contrary to mutations such as in breast cancer type 1 (BRCA1) & breast cancer type 2 (BRCA2) that, when present, predict an approximate 70% chance of the development of breast cancer by the age of 80." (PMID 33667227, 2021). "As a result, it was assumed that BRCA1-mutant breast cancer arose from a basal progenitor/stem cell." (PMID 34587981, 2021). "BRCA1 and BRCA2 are the most commonly mutated breast cancer susceptibility genes that convey a high risk of breast and ovarian cancer." (PMID 34456966, 2021). "Male BRCA1 and BRCA2 carriers are also at an increased risk of breast cancer with risk estimates of ~1–5% and 5–10% respectively, compared with the general male population where the life-time risks are ~0.1%." (PMID 34439109, 2021). "Inherited variants in the cancer susceptibility genes, BRCA1 and BRCA2 account for up to 5% of breast cancers." (PMID 34287743, 2021). "Breast cancer specific survival was good for 119 BRCA1/2 carriers with 20-year survival in BRCA1:91.2% (95% CI 77.8–96.6) and 83.8% (62.6–93.5) for BRCA2." (PMID 34312777, 2021). "Although post-surgical satisfaction is reported by most patients who received CRRM, 57.7% of BRCA1/2 carriers forego the choice of CRRM before or after the surgery for primary breast cancer." (PMID 34563200, 2021). "BRCA2 carriers were diagnosed earlier with breast cancer at 57 years compared to BRCA1 carriers at 62 years." (PMID 34575694, 2021). "In Chinese breast cancer patients, PIK3CA somatic mutations were detected in 14% and 43% of the patients harboring germline BRCA1/BRCA2 mutations (vs. wild type carriers), respectively." (PMID 34287479, 2021). "We further demonstrated that combined treatment of Brca1-mutant mammary tumors with irradiation and AZD2281, which inhibits PARP, significantly reduced tumor progression and extended survival." (PMID 33767581, 2021). "Germline mutations in the genes BRCA1 and BRCA2 are known to predispose women to ovarian and breast cancers." (PMID 33750420, 2021). "In conclusion, we recommend that a molecular test for BRCA1, BRCA2, PALB2 and CHEK2 recurrent mutations should be offered to male breast cancer patients in Poland." (PMID 34461861, 2021). "Targeting autophagy synergistically enhanced the therapeutic efficacy of talazoparib in BRCA1-WT breast cancer cells in vitro and in vivo xenograft tumour mouse model." (PMID 33473172, 2021). "At the mid-1990s, the role of BRCA1 and BRCA2 mutations in elevating breast cancer risk was considered." (PMID 33805996, 2021). "Given the breast cancer risk, future studies on RAD51C and EC risk will need to account for tamoxifen exposure, same as for BRCA1/2 genes." (PMID 33917078, 2021). "In humans, TMEM135 was identified as an apoptosis-regulating protein in BRCA1-mutant estrogen receptor-positive breast cancer." (PMID 34359920, 2021). "We also analyzed mammary tumors developed in Brca1 mutant mice and discovered that 45.83% (11/24) of them were TNBCs." (PMID 34514747, 2021). "Inherited mutations in two different genes (BRCA1 and BRCA2) lead to increased risk of breast cancer." (PMID 34171558, 2021). "Based on our findings, there was a significant increase in the expression levels of phosphorylated histone H2A.X, ATM, CHK1, CHK2, and BRCA1 in both breast cancer cell lines which suggested that ATM acts as the key regulator in 6-gingerol-induced DDR." (PMID 33925065, 2021).
breast cancer (continued). "The association of germline BRCA1 and BRCA2 PGVs with high-risk breast cancer predisposition has been well recognized and clinical diagnostic testing of these genes has been offered for the past 23 years in Manchester." (PMID 34113003, 2021). "The MMTV-Neu (NEU) tumor was ER–/PR–/HER2+, while the MMTV-PyMT (FF99WT) tumor was ER–/PR–/HER2low; the BRCA1-null (BRCA1) tumor which mimics basal-like breast cancers was ER–/PR–/HER–, and the 4T1 transplant tumor was a known ER–/PR–/HER– mouse model." (PMID 34497807, 2021). "Our finding demonstrates that GATA3 functions downstream of BRCA1 to suppress EMT in controlling mammary tumor initiation and metastasis." (PMID 34373738, 2021). "A research based on the analysis of a large number of breast cancer cases confirmed that BRCA1 is abnormally methylated in sporadic tumors and methylation of BRCA1 played a key role in breast tumorigenesis." (PMID 34778045, 2021). "Results showed that BRCA1 gene hypermethylation should be suspected in all breast cancer patients with advanced disease stages, positive lymph nodes, and premenopausal age at diagnosis." (PMID 33808555, 2021). "Results of studies about breast cancer risk in women with these mutations by age 70 have been in range of 44 -78% of women with BRCA1 mutations and 31 -56 % with BRCA2 mutations with increased breast cancer." (PMID 34710987, 2021). "BRCA-related breast cancers have distinct biological features, including a tendency for hormone receptor-negativity in BRCA1 carriers and hormone receptor positivity in BRCA2 carriers." (PMID 33579978, 2021). "We are, hence, currently preparing a meta-analysis in which we will examine the effect of BRCA1 and BRCA2 mutations on the occurrence of breast cancer." (PMID 33925599, 2021). "Evidenced-based management of individuals with confirmed high penetrance pathogenic variants such as BRCA1 and BRCA2 can result in earlier detection of breast cancer when early and timely screening using optimal detection methods is applied." (PMID 33507482, 2021). "BRCA1 and BRCA2 mutations result in 70% risk of developing breast cancer by the age of 80, compared to 12% of the unaffected population." (PMID 34830851, 2021). "The secondary exploratory aim of this study was to evaluate the association of germline BRCA1/BRCA2 mutations with somatic PIK3CA mutations in a cohort of young and postmenopausal patients with breast cancer." (PMID 34287479, 2021). "A founder mutation of BRCA1, BRCA2, CHEK2, PALB2 and NBN was found in 13.3% of men with breast cancer in Poland." (PMID 34461861, 2021). "Germline mutations in BRCA1 and BRCA2 account for around 25% of familial breast cancer clustering and 5–10% risk of all breast cancer cases." (PMID 34207556, 2021). "This meta-analysis showed that BRCA1 gene hypermethylation in breast cancer significantly correlated with advanced disease stage, lymph nodal involvement, and pre-menopausal age at diagnosis." (PMID 33808555, 2021). "Consistent with its similar molecular functions to BRCA1 and BRCA2, monoallelic germline mutations in PALB2 also confer a high risk of breast cancer and increase the risk of ovarian and pancreatic cancers." (PMID 33893322, 2021).
breast cancer (continued). "Previous findings have reported that CS expression is amenable to interference using shRNA approaches, as seen for CS-mediated regulation of the BRCA1 protein in breast cancer cells." (PMID 33807987, 2021). "One study reported a 72% lifetime risk of breast cancer and a 44% lifetime risk of OVCA for females with BRCA1 mutations and lifetime risks of 69% for breast cancer and 17% for OVCA for females with BRCA2 mutations." (PMID 34208188, 2021). "Sporadic breast cancers exhibit BRCA1 downregulation correlated with tumor grade, rate of tumor progression, and risk of metastasis." (PMID 34638264, 2021). "Rare high-risk mutations, particularly in the BRCA1 and BRCA2 genes, explain less than 20% of the twofold familial relative risk (FRR) and account for a small proportion of breast cancer cases in the general population." (PMID 33632172, 2021). "To further dissect the molecular features of the mammary tumors, we checked the relative activation levels of several key pathways involved in mammary development and tumorigenesis, and/or biological functions of BRCA1." (PMID 34815798, 2021). "The tumor-suppressor genes BRCA1 and BRCA2 are the principal genes responsible for inherited cancer predisposition—40–80% of mutation carriers will develop a breast cancer in their life-time." (PMID 33917614, 2021). "Despite the unique challenges posed by BRCA1/2 breast cancers, substantial progress in the development of effective therapies for several cancers has been made in recent decades." (PMID 34070674, 2021). "BRCA-1 associated breast cancers are more likely to be triple negative (TNBC), whereas BRCA-2-associated breast cancers are often hormonally driven and human epidermal growth factor receptor 2 (HER2)-negative." (PMID 34573353, 2021). "BRCA1 and BRCA2 mutant genes predispose individuals to an elevated risk of breast cancer, and those with a family history of cancer are recommended to undergo gene detection based on the National Comprehensive Cancer Network (NCCN) guidelines." (PMID 33549054, 2021). "Conclusions: hypermethylation of the BRCA1 gene significantly correlates with advanced breast cancer disease, lymph nodes involvement, and pre-menopausal cancer onset." (PMID 33808555, 2021). "These online and SM-driven communities serve as powerful resources for the BRCA1/2 and breast cancer-affected for the purposes of peer support, information sharing, and community building." (PMID 35052215, 2021). "In this study we assessed the association of a comprehensive set of SNPs of VDR and GC genes and breast cancer prognosis in a cohort of 368 breast cancer patients with a positive family history of cancer but wild type for BRCA1 and BRCA2." (PMID 33917614, 2021). "Multidisciplinary groups treating women with breast cancer should take into account the possibility of addressing patients with these characteristics with a BRCA1 gene methylation status analysis." (PMID 33808555, 2021). "In tumor cell lysates, PARP activity is inhibited >90% at 100 nM olaparib, and in colony forming assays, an EC50 value of ~250 nM olaparib was observed with a BRCA1-mutant breast cancer line incubated for 7–14 days." (PMID 34945003, 2021). "A clinical trial (NCT00494234) for a poly adenosine diphosphate-ribose polymerase (PARP) inhibitor, olaparib, in patients with BRCA1 or BRCA2 mutations and advanced breast cancer, provided an impressive ORR of 44%." (PMID 34396843, 2021). "In total, 61 BRCA1, 128 BRCA2 and 11 both BRCA1 and BRCA2 genes associated breast cancer patients’ data were used to train the system using Mamdani’s Fuzzy Inference Method and Feed-Forward Neural Network Method as the model softwares on MATLAB." (PMID 34828379, 2021).
breast cancer (continued). "BRCA1 and BRCA2 are the most prominent breast cancer susceptibility genes that convey high risk of breast and ovarian cancers." (PMID 34490083, 2021). "Women who carry the BRCA1 and BRCA2 germline pathogenic variant (BRCAm) have a high lifetime risk of breast cancer (BC) and ovarian cancer (OC)." (PMID 34356116, 2021). "Nevertheless, BRCA1 gene silencing was found to be a very frequent event in sporadic breast cancer, and it has been correlated with its progression and overall survival." (PMID 33808555, 2021). "The aim of the present meta-analysis was to analyze all available studies reporting clinical characteristics of BRCA1 gene hypermethylated breast cancer in women, and to pool the results to provide a unique clinical profile of this cancer population." (PMID 33808555, 2021). "To exclude the influence of BRCA1/2, we found that MEIOB expression was mutually exclusive with mutations in BRCA1/2 in both breast cancers and TNBCs (P < 0.01)." (PMID 33628586, 2021). "The BRCA1 and BRCA2 genes are highly penetrant susceptibility genes for hereditary breast cancer with pathogenic variants found in 5–10% of unselected subjects." (PMID 34196900, 2021). "Since their discovery over three decades ago, the breast cancer 1 (BRCA1) and 2 (BRCA2) genes remain the most clinically significant breast cancer predisposition genes." (PMID 34771713, 2021). "In 1999, Chuxia Deng and colleagues succeeded in developing a mouse model that ablated BRCA1 specifically in mammary epithelial cells, resulting in mammary tumors." (PMID 33842308, 2021). "PARGi is also synthetically lethal in BRCA1, BRCA2, PALB2, FAM175A and BARD1 deficient breast cancer cells." (PMID 33674744, 2021). "This large unique dataset allowed an in-depth investigation of the impact of the type of mutated gene (BRCA1 vs BRCA2) and hormone receptor status on clinical behavior and outcomes of BRCA-mutated breast cancer in young women." (PMID 33579978, 2021). "For example, on the top screen of PICKLES, check “Breast cancer” in the “Cancer type” field, enter “PARP1” in the “Primary gene” field, and “BRCA1” in the “Secondary gene” field (the results of mutation and copy number are reflected in the Secondary gene)." (PMID 34830205, 2021). "Across medical sociology, a number of scholars have considered personal experiences of breast cancer diagnosis, including of molecular diagnostics through the case of germline BRCA1/2 genetic testing." (PMID 33940433, 2021). "Similar to its impact on BRCA-knockout cells, MED12 depletion promoted olaparib and cisplatin resistance in BRCA1-mutant MDA-MB-436 breast cancer cells and BRCA2-mutant PEO1 ovarian cancer cells." (PMID 34871431, 2021). "Differential gene expression analysis showed only subtle variation between germline and somatic mutations for BRCA1 and BRCA2 genes in ovarian and breast cancers." (PMID 33525353, 2021). "Although there is no clinically approved drugs or small molecules available so far to confer such benefit to clinical practice, hope has rooted in the successful utilization of PARP inhibitors in BRCA1/2 mutant breast cancers." (PMID 33692331, 2021). "Our finding identifies GATA3 as the first transcription factor that functions downstream of BRCA1 to suppress EMT in breast cancers." (PMID 34373738, 2021). "Increase in VEGF and HIF1α expression has been observed in BRCA1/2-related and hereditary breast cancer when compared to sporadic breast cancer as well as in BRCA1/2-related hereditary breast cancer compared to other types of hereditary breast cancer." (PMID 33540843, 2021). "CHEK2: After BRCA1 and BRCA2, this was the first breast cancer moderate risk gene to be identified after observing a common deletion (1100delC) in non-BRCA breast cancer families." (PMID 34439109, 2021).